SLFN11 (schlafen family member 11)
Description:
Inhibitor of DNA replication that promotes cell death in response to DNA damage. Acts as a guardian of the genome by killing cells with defective replication. Persistently blocks stressed replication forks by opening chromatin across replication initiation sites at stressed replication forks, possibly leading to unwind DNA ahead of the MCM helicase and block fork progression, ultimately leading to cell death. Upon DNA damage, inhibits translation of ATR or ATM based on distinct codon usage without disrupting early DNA damage response signaling. Antiviral restriction factor with manganese-dependent type II tRNA endoribonuclease. A single tRNA molecule is bound and cleaved by the SLFN11 dimer. Specifically abrogates the production of retroviruses such as human immunodeficiency virus 1 (HIV-1) by acting as a specific inhibitor of the synthesis of retroviruses encoded proteins in a codon-usage-dependent manner. Impairs the replication of human cytomegalovirus (HCMV) and some Flaviviruses. Exploits the unique viral codon bias towards A/T nucleotides. Also acts as an interferon (IFN)-induced antiviral protein which acts as an inhibitor of retrovirus protein synthesis.
Synonyms: FLJ34922; SLFN8/9
Tractability: Small molecule: a structure with a bound ligand is known. PROTAC: ubiquitination databases record sites on it; its protein half-life has been measured.
Target class: Enzyme; Hydrolase
Gene: Protein-coding gene on chromosome 17 (35,350,305 to 35,373,701, reverse strand). Ensembl gene ENSG00000172716.
Subcellular location: Nucleus; Chromosome
Subcellular location (Human Protein Atlas): Nucleoplasm; Cytosol
Gene Ontology:
Molecular function: ATP hydrolysis activity; protein binding; tRNA binding; catalytic activity
Biological process: chromatin remodeling; defense response to virus; DNA damage response; negative regulation of DNA replication; negative regulation of G1/S transition of mitotic cell cycle; replication fork arrest
Cellular component: chromosome; nucleoplasm; nucleus; site of DNA damage
Genetic constraint (gnomAD): Loss-of-function variants: 34 observed, 43.15 expected, observed/expected ratio (o/e) 0.79, 90% interval 0.6 to 1.05. The upper end of that interval is the gene's LOEUF score, 1.05, which puts it in group 4 of 6, group 1 being the genes least tolerant of losing a copy. Missense variants: 829 observed, 901.03 expected, observed/expected ratio (o/e) 0.92, 90% interval 0.87 to 0.97. Synonymous variants: 325 observed, 324.46 expected, observed/expected ratio (o/e) 1, 90% interval 0.91 to 1.1.
Homologues: Orthologues: chimpanzee SLFN11 (98% identical), mouse Slfn9 (61% identical), mouse Slfn10 (61% identical), rat Slfn9 (61% identical), mouse Slfn8 (60% identical). Paralogues in human: SLFN13 (77% identical), SLFN5 (51% identical), SLFN14 (44% identical), SLFN12 (25% identical), SLFN12L (25% identical), SLFNL1 (9% identical).
Diseases named in the same sentence as SLFN11 in open-access papers:
SLFN11 is named in the same sentence as 91 diseases in open-access papers, as found by Europe PMC text mining. Sharing a sentence is not in itself a finding about the gene and the disease. The quoted sentences say what the papers report.
small cell lung carcinoma (28 papers, 2016 to 2025). Small cell lung cancer (SCLC) is a highly aggressive malignant neoplasm, accounting for 10-15% of lung cancer cases, characterized byrapid growth, and early metastasis. "While elevated SLFN11 levels in small cell lung cancer cells were associated with sensitivity to PARPi, this correlation was more pronounced, particularly with the highly potent PARP trapper talazoparib." (PMID 38255825, 2024). "Expression of SLFN11 has been associated with improved response to DNA-damaging agents in ovarian cancer and small cell lung cancer, and enhancing expression of SLFN11 is a potential strategy under investigation to sensitise tumours to PARPi and other DNA-damaging agents." (PMID 37430137, 2023). "Results reported by a study investigating small cell lung cancer (SCLC) cells demonstrated that the histone deacetylase inhibitor FK228 can induce the re-expression of SLFN11." (PMID 41303540, 2025). "Dynamic expression of SLFN11 in circulating tumor cells can be used as a liquid biomarker for small cell lung cancer, which can predict patient sensitivity to treatment." (PMID 40766331, 2025). "There is increasing evidence that patients with SLFN11-positive solid tumors, such as small cell lung cancer or Ewing sarcoma, respond better to DDA and/or PARPi." (PMID 35625957, 2022). "Enhanced H3K27me3 levels in the gene body of SLFN11, a DNA-damage repair gene, contribute to the resistance for etoposide in a patient-derived xenograft mouse model of small cell lung cancer." (PMID 34725436, 2021). "In small cell lung cancer cells, SLFN11 expression is silenced by marked deposition of H3K27me3, leading to drug resistance, and is reactivated by inhibition of EZH2 a methyltransferase for H3K27." (PMID 33513156, 2021). "In a recent study, SLFN11 expression correlated with in vivo tumor response to talazoparib in patient-derived xenograft (PDX) models of small cell lung cancer (SCLC)." (PMID 30723695, 2018). "Response to the talazoparib-temozolomide combination was also driven by SLFN11 and validated in 36 small cell lung cancer cell lines, and in xenograft models." (PMID 27708213, 2016). "However, the relationship between SLFN‐11 expression and clinical outcomes in patients with small cell lung cancer (SCLC) remains unexplored." (PMID 39809728, 2025). "Importantly, both combination treatments and doxorubicin treatment alone reduced SLFN11 expression, which was described as a factor in acquired chemoresistance in small-cell lung cancer patients." (PMID 40134582, 2025). "A similar strategy was reported with SLFN11 in small cell lung cancer." (PMID 40271221, 2025). "The promising method for allowing SLFN11 expression to be tracked longitudinally in a non-invasive manner during the course of the disease seems to be an assessment on circulating tumor cells, as has been described recently in small cell lung cancer." (PMID 35625957, 2022). "The presence of SLFN11 was found to be associated with sensitivity to DDA and PARPi across a variety cancer cell lines and patient-derived xenografts, including small cell lung cancer, colorectal cancer, sarcoma, gastric cancer, mesothelioma, and ovarian cancer." (PMID 35625957, 2022). "However, inhibition of EZH2 expression or its methyltransferase activity promoted chemosensitivity through the induction of SLFN11 expression in small cell lung cancer, which is contrary to our results in CRC." (PMID 31065671, 2020). "Generation of paired chemonaive and chemoresistant small cell lung cancer (SCLC) PDX models led to the finding that EZH2 promotes chemoresistance by epigenetically silencing SLFN11, and EZH2 inhibition prevents acquisition of chemoresistance and improves chemotherapeutic efficacy in SCLC." (PMID 28499452, 2017).
small cell lung carcinoma (continued). "In addition, SLFN11, as a general target, is considered to exert a vital regulatory function in improving the sensitivity of multiple malignancies to chemotherapy, such as ovarian cancer, prostate cancer, small cell lung cancer, and so on." (PMID 36211333, 2022). "Knockdown of SLFN11 has shown to result in decreased sensitivity to the DNA damaging cytotoxic agent trabectedin in preclinical liposarcoma and Ewing sarcoma (ES) models and decreased sensitivity to the PARPi talazoparib in small cell lung cancer (SCLC) cell lines." (PMID 34085099, 2021). "Furthermore, SLFN11 (Schlafen Family Member 11) is sensitive to PARPi in small cell lung cancer." (PMID 32235451, 2020). "In cancers such as ovarian, breast, gastric, and small cell lung cancer (SCLC), high SLFN11 expression consistently predicts better outcomes in patients treated with DNA-targeting chemotherapy." (PMID 40766331, 2025). "Mechanism 2: Promoter methylation and histone deacetylation: In small cell lung cancer (SCLC) cell lines, SLFN11 expression is often silenced by promoter hypermethylation, which is significantly negatively correlated with SLFN11 expression." (PMID 40766331, 2025). "In small cell lung cancer (SCLC) cells, SLFN11 expression is strongly suppressed by promoter methylation." (PMID 41303540, 2025). "It has been reported that EZH2 promotes chemotherapy resistance by inhibiting Schlafen family member 11 (SLFN11), expression in small cell lung cancer." (PMID 31065671, 2020). "PARPs mediate DNA damage responses and small cell lung cancer (SCLC) PDXs lacking SLFN11 expression were found to be resistant to the PARPi talazoparib as compared to PDXs that expressed high levels of SLFN11." (PMID 38791884, 2024). "SLFN11 overexpression in GR-CDXL4 led to olaparib sensitivity and was in coherence with neuroendocrine marker expression in patient tumor biopsy, suggesting a predictive value of SLFN11 in NSCLC histological transformation into small cell lung cancer (SCLC)." (PMID 35511434, 2022). "Cancer patients whose tumors show high SLFN11 expression show better chemotherapy response to PARP inhibitors, irinotecan, and temozolomide in recurrent or refractory solid tumors such as Ewing sarcoma and small cell lung cancers (SCLCs)." (PMID 34572827, 2021). "In tumors with low SLFN11 expression, such as ovarian cancer, breast cancer, colorectal cancer, small - cell lung cancer, and bladder cancer, combine chemotherapy with HDAC inhibitors or demethylating agents to verify whether they can enhance chemotherapy sensitivity by upregulating SLFN11." (PMID 40766331, 2025).
breast carcinoma (18 papers, 2016 to 2025). "It is important to note that subgroups of breast cancer and high-grade serous ovarian carcinoma patients with high SLFN11 expression showed a prominent association with immune activation after treatment with chemotherapy." (PMID 39588782, 2024). "Survival analysis of clinical samples showed that breast cancer patients with high SLFN11 expression who received chemotherapy (unspecified drug) had a significant OS advantage." (PMID 40766331, 2025). "Breast cancer samples with high SLFN11 expression were accompanied by enhanced immune response characteristics, including T cell infiltration and high expression of immune checkpoints (such as PD-L1)." (PMID 40766331, 2025). "This association was further supported at the patient level and in models: breast cancer patients with high SLFN11 protein expression responded significantly better to standard chemotherapy with DNA damaging agents (DDAs), such as gemcitabine and cisplatin." (PMID 40766331, 2025). "Most intriguingly, recent findings suggest SLFN11’s involvement in immune regulation, particularly in promoting T-cell infiltration and activation in breast cancer, underscoring its multifaceted role in both cancer therapy and immune modulation." (PMID 40740189, 2025). "When only analyzing breast cancer patients who received chemotherapy (n = 34), patients with high SLFN11 expression showed a significant benefit in overall survival (OS) (p = 0.048)." (PMID 40766331, 2025). "The expression of SLFN11 is strictly regulated in breast cancer, and its promoter methylation is an important mechanism leading to the downregulation of its mRNA and protein expression." (PMID 40766331, 2025). "The MCF7 breast cancer cell line endogenously expresses relatively lower levels of SLFN11 and abundant full-length LINE-1 transcripts, making them suitable for ChIP analysis." (PMID 40497966, 2025). "In order to re-establish normal SLFN11 expression through demethylation of the SLFN11 gene in the selected breast cancer cell lines, we treated them with 5 μm of DAC for 72 h." (PMID 38001424, 2023). "Since SLFN11 expression is interferon inducible, our next approach was to treat breast cancer cells with 5 nM of IFN-γ for 24 h." (PMID 38001424, 2023). "In this study, we examined various approaches to elevate SLFN11 expression in breast cancer cellular models and confirmed a corresponding increase in chemosensitivity with using the most successful efficient one." (PMID 38001424, 2023). "First, we screened SLFN11 expression in a panel of 48 cell lines including 27 breast cancer cell lines." (PMID 37567892, 2023). "Our results demonstrated that decitabine not only enhanced TROP2 expression, but also increased SLFN11 expression in these breast cancer cells." (PMID 37567892, 2023). "As a secondary approach to pick up cross talk between immune cells and SLFN11 expression we used indirect co-culture of breast cancer cells with activated PBMCs and evaluated if this can drive SLFN11 upregulation." (PMID 38001424, 2023). "Breast cancer cohorts provided some other interesting findings: they demonstrated elevated SLFN11 in cancers with worse prognosis." (PMID 33339894, 2021). "Regardless, SLFN11 transcript and protein levels strongly correlated in the same breast cancer cohort, demonstrating that transcript and protein assessment equally reflects SLFN11 levels in xenograft tissues." (PMID 33339894, 2021). "We evaluated SLFN11 in different cancer types and correlated it with drug and patient treatment in two different breast cancer cohorts." (PMID 33339894, 2021). "Finally, we attempted to induce increased SLFN11 expression by co-culturing breast cancer cells with PBMC activated by CD3/CD28 for 24 h." (PMID 38001424, 2023). "Therefore, we tried inducing SLFN11 expression using in-vitro Interferon Gamma stimulation in our breast cancer cells." (PMID 38001424, 2023). "Higher SLFN11 gene expression showed a better prognosis in breast cancer." (PMID 38001424, 2023).
breast carcinoma (continued). "Similarly, high SLFN11 expression in breast cancer is related to more aggressive and immune-activated tumors, whereas low SLFN11 expression is associated with low aggressiveness and low immune activation status." (PMID 36090985, 2022). "This could be because high SLFN11 breast cancers are mostly ER-negative, basal-like phenotype that are known for their poor response to hormonal therapy." (PMID 34571887, 2021). "Moreover, SLFN11 has been recently studied in relation with the immune system, especially in breast cancer, and for its potential role as an endogenous inhibitor of viral replication and translation of DNA damage response proteins." (PMID 34549724, 2021). "Further investigation is needed, particularly in ovarian and breast cancers, to determine whether SLFN11 levels play a role in the response to olaparib in the clinic, and whether this is independent of BRCA mutations." (PMID 34663950, 2021). "Indeed, in humans, epidemiologic data suggest that SLFN11 expression is higher in patients with ovarian, lung, or breast cancer who respond to chemotherapy and in patients with gastric carcinoma who survive longer." (PMID 34571887, 2021). "SLFN11 protein associated with both preclinical and patient treatment response to DDA, but not to non-DDA or DDRi therapies, such as WEE1 inhibitor or olaparib in breast cancer." (PMID 33339894, 2021). "For breast cancer patients with low SLFN11 expression, preclinical evidence suggests that the combination of DDA (such as gemcitabine) and ATR/WEE1/CHK1 inhibitors (such as AZD6738) may be an effective treatment strategy to overcome their potential drug resistance." (PMID 40766331, 2025). "Hence, SLFN11 could make for a good predictive biomarker of therapeutic response or a treatment target in many cancers including breast cancer." (PMID 38001424, 2023). "Our results show that induction of SLFN11 expression can enhance DDA and DDR sensitivity in breast cancer cells and dCas9 systems may represent a novel approach to increase SLFN11 and achieve higher sensitivity to chemotherapeutic agents, improving outcome or decreasing required drug concentrations." (PMID 38001424, 2023). "Because SLFN11 determines response to a wide range of DNA damaging drugs in addition to PARPIs, further clinical studies and assays are warranted to score SLFN11 expression in tumor samples like estrogen receptor is examined routinely by immunohistochemistry in breast cancer." (PMID 27708213, 2016). "For example, SLFN5 and SLFN12 exhibit positive feedback in breast cancer, while SLFN5, SLFN11, and SLFN13 all play roles in HIV-1 regulation." (PMID 39558948, 2024). "Based on the screening results we selected 3 representative breast cancer cell lines (BT-549, T47D and MDA-MB-231) for further experiments as they cover the range of SLFN11 expression observed at baseline (moderate, low and null compared to HFF)." (PMID 38001424, 2023). "Analysis by Q-RT-PCR confirms differential SLFN11 mRNA expression among multiple breast cancer cell lines; however, MDA-MB-231, MDA-MB-543 and HCC70 showed almost null SLFN11 mRNA expression (N = 3)." (PMID 38001424, 2023). "Human SLFN5, SLFN11, SLFN12, SLFN13, and SLFN14 are all downregulated in breast cancer, lung squamous carcinoma, prostate cancer, and rectal carcinoma." (PMID 34571887, 2021). "Since SLFN11 has been reported as an interferon inducible gene, and interferon is secreted during an active anti-tumor immune response, we investigated the in vitro effect of IFN-γ on SLFN11 expression in breast cancer cell lines." (PMID 38001424, 2023). "Cell lines that completely lack SLFN11 expression due to strong promoter hypermethylation such as MDA-MB-231 breast cancer cell lines, did not exhibit an increase in SLFN11 expression upon dCas9 CRISPR activation." (PMID 38001424, 2023). "Moreover, SLFN11 positively correlates with markers of lymphocytic tumor infiltration such as CD3 and CD8 in breast cancer." (PMID 34571887, 2021).
breast carcinoma (continued). "SLFN11 was absent in tumour cells in 71% of patients with breast cancer (n = 17), the two highest SLFN11 expressors were TNBC." (PMID 34663950, 2021). "We next assessed SLFN11 protein by IHC in a second PDX cohort of breast cancers (N = 68), where patients had mainly received DDA and non-DDA-based chemotherapy treatment." (PMID 33339894, 2021). "When analyzing only breast cancer patients who received chemotherapy (drugs not specified), there was a significant OS benefit in patients with high SLFN11 expression (HR = 4.32, p = 0.017)." (PMID 31682620, 2019). "Besides, DAC treatment did not significantly affect the methylation of SLFN11 promoter in BT-549 and T47D breast cancer cell lines." (PMID 38001424, 2023). "Taken together, these findings indicate that SLFN11 is correlated with both preclinical and clinical response to DDA therapies in breast cancer and that SLFN11 low or absent tumours are less responsive to DDA treatment." (PMID 33339894, 2021). "In a multidisciplinary effort, combining different analyses in multiple cancer models and types, we demonstrate that SLFN11 represents an important biomarker for the stratification of DDA therapies, but not to DDRi monotherapies in breast cancer." (PMID 33339894, 2021). "Unlike the observation with SLFN11, SLFN12 expression is correlated with endocrine therapy sensitivity in estrogen-positive breast cancer, as SLFN12 is one of the 60 differentially methylated region (DMR) genes in breast cancers with endocrine resistance." (PMID 34571887, 2021).